SEC16A (SEC16 homolog A, endoplasmic reticulum export factor)
Description:
Acts as a molecular scaffold that plays a key role in the organization of the endoplasmic reticulum exit sites (ERES), also known as transitional endoplasmic reticulum (tER). SAR1A-GTP-dependent assembly of SEC16A on the ER membrane forms an organized scaffold defining an ERES. Required for secretory cargo traffic from the endoplasmic reticulum to the Golgi apparatus. Mediates the recruitment of MIA3/TANGO to ERES. Regulates both conventional (ER/Golgi-dependent) and GORASP2-mediated unconventional (ER/Golgi-independent) trafficking of CFTR to cell membrane. Positively regulates the protein stability of E3 ubiquitin-protein ligases RNF152 and RNF183 and the ER localization of RNF183. Acts as a RAB10 effector in the regulation of insulin-induced SLC2A4/GLUT4 glucose transporter-enriched vesicles delivery to the cell membrane in adipocytes (By similarity).
Synonyms: p250; KIAA0310; SEC16L
Tractability: Antibody: UniProt places it where antibodies can reach, with high confidence. PROTAC: ubiquitination databases record sites on it; its protein half-life has been measured.
Gene: Protein-coding gene on chromosome 9 (136,440,096 to 136,483,843, reverse strand). Ensembl gene ENSG00000148396.
Subcellular location: Endoplasmic reticulum membrane; Golgi apparatus membrane; Cytoplasm, perinuclear region; Cytoplasm, cytosol; Microsome membrane
Subcellular location (Human Protein Atlas): Golgi apparatus; Endoplasmic reticulum
Pathways (Reactome):
Vesicle-mediated transport: COPII-mediated vesicle transport
Gene Ontology:
Molecular function: protein binding; protein-membrane adaptor activity
Biological process: COPII vesicle coating; endoplasmic reticulum organization; endoplasmic reticulum to Golgi vesicle-mediated transport; Golgi to plasma membrane transport; protein stabilization; response to endoplasmic reticulum stress; substantia nigra development; endocytic recycling; intracellular protein localization; localization within membrane
Cellular component: cytosol; endoplasmic reticulum; endoplasmic reticulum exit site; endoplasmic reticulum membrane; Golgi apparatus; organelle membrane; ER to Golgi transport vesicle membrane; perinuclear region of cytoplasm; Golgi membrane
Genetic constraint (gnomAD): Loss-of-function variants: 109 observed, 205.74 expected, observed/expected ratio (o/e) 0.53, 90% interval 0.45 to 0.62. The upper end of that interval is the gene's LOEUF score, 0.62, which puts it in group 2 of 6, group 1 being the genes least tolerant of losing a copy. Missense variants: 3,119 observed, 3,064.2 expected, observed/expected ratio (o/e) 1.02, 90% interval 0.99 to 1.05. Synonymous variants: 1,373 observed, 1,244.5 expected, observed/expected ratio (o/e) 1.1, 90% interval 1.05 to 1.15.
Homologues: Orthologues: chimpanzee SEC16A (98% identical), macaque SEC16A (94% identical), dog SEC16A (72% identical), mouse Sec16a (71% identical), rat Sec16a (71% identical), guinea pig SEC16A (67% identical), pig SEC16A (67% identical), tropical clawed frog sec16a (45% identical), Drosophila melanogaster Sec16 (19% identical), Caenorhabditis elegans sec-16A.2 (13% identical). Paralogues in human: SEC16B (15% identical).
Diseases named in the same sentence as SEC16A in open-access papers:
SEC16A is named in the same sentence as 28 diseases in open-access papers, as found by Europe PMC text mining. Sharing a sentence is not in itself a finding about the gene and the disease. The quoted sentences say what the papers report.
breast carcinoma (2 papers, 2020 to 2021). "UCD178 also contains a SEC16A-NOTCH1 fusion protein occasionally found in breast cancers." (PMID 32576280, 2020).
Obesity (2 papers, 2018 to 2023). Accumulation of substantial excess body fat. "Novel targets include MYO18A, SEC16A, CCNB1, MAD2L1, hsa-mir-4315, hsa-mir-6134, hsa-mir-9500, KIFC3, FBL (fibrillarin), TUBA1A and GFI1B might have crucial biologic functions in the pathogenesis of patients with diabetes mellitus and obesity." (PMID 36837510, 2023).
viral infection (2 papers, 2012 to 2024). "A similar scenario is proposed here where, in response to viral infection, the association of TRAF3 with complexes containing p115 and Sec16A at the ER-to-Golgi vesicular pathway may play an important role in positioning TRAF3 with MAVS." (PMID 22792062, 2012). "However, following viral infection, the response was increased in cells overexpressing Sec16A or p115." (PMID 22792062, 2012). "Reciprocally, mild overexpression of Sec16A or p115 in Hec1B cells increased the activation of IFNβ, ISG56 and NF-κB -dependent promoters following viral infection and ectopic expression of MAVS and Tank-binding kinase-1 (TBK1)." (PMID 22792062, 2012). "Analysis of ER stress makers revealed higher ER stress levels in pancreatic acinar cells of Sec16a+/− mice compared to Sec16a+/+ mice, even without viral infection or cerulein stimulation (blue dots)." (PMID 39119875, 2024). "However, upon viral infection or transfection with poly I:C or poly dA:dT, immunocomplexes containing endogenous TRAF3 were enriched with p115 and Sec16A." (PMID 22792062, 2012). "Finally, TEM evaluation of isolated pancreatic cells (without viral infection or cerulein stimulation) from Sec16a+/− mice showed increased intracellular vacuolization and visible ER dilations with protein overload compared to Sec16a+/+ mice." (PMID 39119875, 2024). "Thus, we propose that these two trafficking proteins, Sec16A and p115, form a complex with TRAF3 at ER-to-Golgi transport compartments in order to ensure its proper recruitment to the mitochondrial network during a viral infection." (PMID 22792062, 2012).
acute pancreatitis (1 paper, 2024). An acute inflammatory process that leads to necrosis of the pancreatic parenchyma. "Among 16 Chinese teenage CP patients subjected to trio exome sequencing, a 12‐year‐old boy with a history of recurrent acute pancreatitis was found to harbor a heterozygous de novo frameshift variant, c.6491_6492delTG (p.Val2164AlafsTer20), in the SEC16A gene." (PMID 39119875, 2024).
Autoimmunity (1 paper, 2019). The occurrence of an immune reaction against the organism's own cells or tissues. "A blood brain barrier phenotype is present as well as autoimmunity and autophagy with ANO2, HLA-DQB1, MTMR3, and SEC16A." (PMID 31026304, 2019).
chronic pancreatitis (1 paper, 2024). A chronic inflammatory process causing damage and fibrosis of the pancreatic parenchyma. "Here, a link between rare SEC16A variants and chronic pancreatitis, demonstrating that loss of SEC16A function disrupts ER‐to‐Golgi trafficking of secretory proteins in pancreatic acini is identified." (PMID 39119875, 2024).
ischemic stroke (1 paper, 2025). A stroke disorder caused by obstruction of blood flow to the brain, due to thrombotic (local blood clot formation) or embolic (due to a blood clot or other material traveling from another site) event. "In ischemic stroke, we found that MPO, CALCRL, PPP5C, KTN1-AS1, CCR1, CTB-50L17.9, CCR9, ZNF362, ZIK1, ELP5, CKAP2, NUP88, and SEC16A show risk effects (OR > 1)." (PMID 40624693, 2025).
Myocardial fibrosis (1 paper, 2024). "During myocardial fibrosis, it is crucial to explore the molecular mechanisms involved in the rapid recruiting of SEC16A, initiating ERES assembly, and meeting the high demand for collagen secretion." (PMID 38515161, 2024).
pancreatitis (1 paper, 2024). Inflammation of the pancreas. "In short, our mouse studies confirmed that the loss of SEC16A function increases susceptibility to severe and progressive pancreatitis by impairing ER‐to‐Golgi transport and inducing ER stress." (PMID 39119875, 2024). "Findings from the variant knock‐in cell model were further validated using Sec16a+/− mice, which exhibited more severe pancreatitis under cerulein stimulation compared to their wild‐type counterparts." (PMID 39119875, 2024). "Cerulein‐induced pancreatitis in Sec16a+/− mice was characterized by an increased infiltration of inflammatory cells, including CD45 leukocyte and F4/80 macrophages." (PMID 39119875, 2024). "In cerulein‐stimulated pancreatitis models, Sec16a+/− mice display heightened pancreatic inflammation and fibrosis compared to wild‐type mice." (PMID 39119875, 2024). "Next, we investigated whether heterozygous knockout of Sec16a affects the severity of pancreatitis in the context of cerulein‐induced AP." (PMID 39119875, 2024). "While normal 8‐week‐old Sec16a+/+ and Sec16a+/− mice showed no significant pancreatic differences, cerulein‐treated Sec16a± mice demonstrated significantly increased severity of pancreatitis compared to cerulein‐treated wild‐type mice." (PMID 39119875, 2024).
Parkinson disease (1 paper, 2018). A progressive degenerative disorder of the central nervous system characterized by loss of dopamine producing neurons in the substantia nigra and the presence of Lewy bodies in the substantia nigra and locus coeruleus. "Furthermore, a recent report indicated that Sec16A interacts with the GTPase domain of LRRK2, a protein produced by the causative gene for Parkinson’s disease, and observed that LRRK2 regulates the function of Sec16A." (PMID 29300766, 2018).
spondyloarthritis (1 paper, 2018). "In frame deletions of SeC16A have been observed in familial forms of spondyloarthritis." (PMID 29510755, 2018).
infection (4 papers, 2012 to 2023). The state of being infected such as from the introduction of a foreign agent such as serum, vaccine, antigenic substance or organism. "Quantification of viral replication by luminescence measurement on cell lysates revealed that down-regulation of Syn5 or Sec16A both induced a 30–40% decrease in the infection." (PMID 38203585, 2023).
cancer (3 papers, 2021 to 2024). A tumor composed of atypical neoplastic, often pleomorphic cells that invade other tissues. "The intersection of these lists revealed that three genes (MUC2, CRACR2A, SEC16A) were significantly up-regulated in carcinomas-muc of all tested cancer types compared to controls." (PMID 33947930, 2021). "We hypothesize that carcinomas-muc up-regulates SEC16A to sustain mucin secretion." (PMID 33947930, 2021). "In this study, we have demonstrated that the up-regulation of MUC2, SEC16A and CRACR2A is the common denominator of all carcinomas with mucinous differentiation studied here." (PMID 33947930, 2021). "Fifty of fusion genes have been reported and 14 involving known cancer genes (ALDH2-ACAD10, BIRC6-SPAST, BIRC6-TTC27, CGNL1-TCF12, CPEB3-IDE, CTNNA1-KDM3B, DNAJB1-PRKACA, LRP5-CHKA, PPFIBP1-STK38L, RNF213-SLC26A11, RXRA-WDR5, SEC16A-NOTCH1, WNK1-ERC1, and ACVR1B-ACVRL1)." (PMID 37403120, 2023).
autosomal recessive disease (1 paper, 2021). Autosomal recessive form of disease. "INPP5E were associated with autosomal recessive diseases, while SEC16A had not been reported to be related to a known disease." (PMID 33898534, 2021).
SEC16A also shares sentences with these, for which no sentence is quoted: tumor (3 papers); acute myeloid leukemia (1); colon cancers (1); colonic adenocarcinoma (1); colorectal cancer (1); cyst (1); diabetes mellitus (1); Granuloma (1); lentivirus infection (1); liver cancer (1); lung carcinoma (1); melanoma (1); sarcoidosis (1); type 2 diabetes (1).